CRP (C-reactive protein)
Diseases named in the same sentence as CRP in open-access papers (continued):
Sharing a sentence is not in itself a finding about the gene and the disease.
cognitive decline (continued). "After 11 years of follow-up, the 5 blood-based markers that correlated best with cognitive decline were APOE (present/absent), cystatin C, serum glucose, CRP, and IL-6." (PMID 33946285, 2021). "There are several other inflammatory markers that were not assessed; however, CRP, IL-6, sTNF-RII, and IL-1ra were chosen because previous studies have demonstrated these markers to be elevated and correlated with cognitive decline in BCS." (PMID 30126098, 2018). "C-reactive protein (CRP) is a marker of nonspecific acute-phase response in inflammation, infection and tissue damage, correlated with cognitive decline." (PMID 26106326, 2015).
renal failure (176 papers, 2006 to 2026). "In this way, kidney failure and high CRP and LDH levels are significantly associated with an increase in mortality." (PMID 39189008, 2024). "Renal insufficiency was significantly associated with age, peripheral manifestation, serum albumin, C-reactive protein and erythrocyte sedimentation rate." (PMID 31620002, 2019). "Further Cox proportional hazards analysis revealed that children in the high NLR and high CRP groups were at an increased risk of relapse, rehospitalization, infection, prolonged cumulative steroid use, renal insufficiency, secondary hypertension, and other adverse outcomes within one year." (PMID 40078589, 2025). "On univariate logistic regression, the presence of kidney failure, CRP level, leukocyte count and blood glucose levels were significantly associated with PET/CT reports." (PMID 40257695, 2025). "Levels of inflammation are highest in people with kidney failure, with large cohort studies indicating that 30%–60% of haemodialysis patients have substantially increased C-reactive protein (CRP) levels." (PMID 40235955, 2025). "Among elderly patients with hip fractures, age, renal insufficiency, antipsychotics, COPD, LDH, and CRP were independent risk factors for POD." (PMID 38267405, 2024). "In terms of the development of kidney failure, significantly elevated CRP values were observed on Days 2 and 3 (p < 0.05), and consistently significantly higher PCT values were measured from Days 1 to 5 (p < 0.01; p < 0.005)." (PMID 39336857, 2024). "Further longitudinal studies with larger sample sizes will help us clarify the relationship between C-reactive protein and interleukins and AS in kidney failure patients undergoing long-term PD." (PMID 39728781, 2024). "After accounting for sex, age, CRP, and smoking status, a lower HALP score was associated with an increased risk for kidney failure and cancer." (PMID 37284646, 2023). "Patients with renal insufficiency, even in the early stage, have been reported to have high expression of inflammatory factors, such as hypersensitive C-reactive protein, interleukin-6 and fibrinogen." (PMID 34674646, 2021). "In patients with kidney failure, restriction in dietary AGEs was associated with a decrease in serum AGE-concentration and CRP-values." (PMID 31936498, 2020). "In accordance with previous reports, the mean level of acute-phase inflammation indicators was also higher in the renal insufficiency group: CRP (15.7 (3.8-50.2) vs 9.9 (2.1-27.5), p = 0.034) and ESR (28.0 (10.0-63.0) vs 15.0 (6.0-38.5), p = 0.011)." (PMID 31620002, 2019). "A significant quantity of assessed parameters showed strong correlations with superoxide-dismutase, renal insufficiency rate, C-reactive protein, and neopterin." (PMID 28122514, 2017). "High concentrations of CRP were predictors for neurological complications in E. coli O157:H7 infected human patients and renal insufficiency in persons with TMA." (PMID 28559930, 2017). "Other predictors of death were WL ≥ 10%, kidney failure, CRP ≥ 2.4 mg/dL, prealbumin <10 mg/dL, albumin <3.00 g/dL and cholinesterase <5064 UI/mL." (PMID 28025528, 2016). "In our study, there was 42 % (10 cases) of SLE patients with the value of CRP higher than 5 mg/L, than majority of them (7 cases) suffered from renal insufficiency with proteinuria." (PMID 24346772, 2014). "C-reactive protein (CRP) levels on admission were significantly higher in patients with renal insufficiency compared to patients with normal renal function." (PMID 22292070, 2012). "Our study showed that NT-proBNP independently predicted ICU mortality in unselected patients even after adjustment for the APACHE II score and other potential confounders, including age, renal insufficiency (eGFR), and inflammation (CRP)." (PMID 21272380, 2011).
renal failure (continued). "The failure of NIPPV treatment leads to the delay of endotracheal intubation time and treatment time, which increases the mortality of patients, which might relate to high CRP concentration, serum albumin, combined renal insufficiency, vomit aspiration." (PMID 37828534, 2023). "Similarly, CRP showed a significant difference between patients with normal renal function and those with renal failure (AKI and/or CKD) at admission to the ICU (p = 0.005) within the “septic” group." (PMID 37238265, 2023). "The treated group had a higher overall risk of comorbidity, whereas the non-supplemented group had lower values of O2 saturation at admission, higher CURB-65 score and higher rate of ARDS moderate or severe, higher levels of inflammatory markers such as CRP, and a higher frequency of kidney failure." (PMID 34064175, 2021). "They concluded that SZ might have a beneficial effect on the serum CRP, especially at a dose of 50 mg/day, and in renal insufficiency adults patients compared with healthy subjects." (PMID 31694220, 2019). "It has been reported that an elevation of either C-reactive protein (CRP) or interleukin-6 (IL-6), as a biomarker of systemic inflammation, was strongly associated with CVD in peritoneal dialysis (PD) patients, as well as risk factors of both all-cause and cardiovascular mortality." (PMID 30445969, 2018). "Their CRP and pro-BnP levels were higher, and more of them had renal insufficiency." (PMID 27221100, 2016). "Age, gender, renal insufficiency (Cr ≥ 69 μmol/L), sST2 ≥ 63.8 ng/ml, TNI ≥ 13.3 ng/L, NT-proBNP ≥ 3182 pg/ml, CRP ≥ 26.5 mg/L and LVEF ≤ 40% were introduced into the logistic regression model and analyzed by applying the forward stepwise method." (PMID 40098635, 2025). "Moreover, PCT and CRP levels may be influenced by renal insufficiency." (PMID 38667467, 2024). "In our cohort, we noted that relative to the onset of renal failure, patients developing AKI in the first week of illness had a favorable clinical status towards recovery, with lower procalcitonin and CRP values." (PMID 37685436, 2023). "This lack in renal replacement therapy-RRT patients (namely in HD and in peritoneal dialysis) could also be related to a lower blood concentration of prealbumin and to an increased inflammatory state, which could be monitored by the concentration of highly sensitive C-reactive protein (hs-CRP)." (PMID 35631140, 2022). "Logistic single factor analysis found that Child-Pugh classification, serum CRP, ascites WBC, ascites ALB, upper gastrointestinal hemorrhage, hepatorenal syndrome and hepatic encephalopathy of the patient were related to liver cirrhosis complicated with SBP." (PMID 30788303, 2018). "In the late 1990s, C-reactive protein (CRP) was acknowledged as powerful predictor of cardiovascular death and overall mortality in HD and peritoneal dialysis (PD) patients." (PMID 30277113, 2018). "Inflammatory markers, such as C-reactive protein (CRP) and procalcitonin, can be elevated in non-infectious conditions like inflammatory diseases or renal insufficiency." (PMID 40001374, 2025). "They show the progressive increase in CRP levels in infected patients, both with and without kidney failure, as well as PCT, reaching their highest value at 72 h." (PMID 36555891, 2022). "Concomitant with these effects on serum TNF-α, IFN-γ, and IL-6 levels, HOMA-IR and HOMA-IS, the CRP (marker of inflammation) was most deleteriously affected in nephrotic diabetic patients without kidney failure." (PMID 33442388, 2020). "Nevertheless, the control group in our study had normal hemoglobin level, WBC counts, neutrophil counts, platelet counts, and CRP level and had no symptoms of active infections, inflammatory diseases, or kidney failure." (PMID 32091174, 2020). "Nevertheless, only a few small studies have assessed the consequences of longitudinal conventional CRP, but not hs-CRP, fluctuation on mortality among peritoneal dialysis (PD) patients." (PMID 28676043, 2017).
renal failure (continued). "Factors associated with improved survival include young males with low International Staging System (ISS) and Durie-Salmon stage, good performance status, and absence of poor prognostic features as high CRP, low hemoglobin, and severe renal insufficiency." (PMID 24558623, 2013). "In hemodialysis patients both baroreflex and nonbaroreflex bsl were inversely correlated to CRP, confirming previous observations on the connection between inflammatory markers and autonomic nervous system dysfunction in severe renal insufficiency." (PMID 24124623, 2013). "The observed inverse association between total fecal ODA and serum proinflammatory markers, such as CRP, IL-6, and MCP-1, suggests that gut microbiota’s ODA may exacerbate chronic inflammation, which is known to play a critical role in the progression of CVD in patients with kidney failure." (PMID 38138292, 2023). "In our study, the level of CRP and ESR were significantly higher in patients with renal insufficiency, but there was no significance in the multivariable logistic regression analysis." (PMID 31620002, 2019). "The sensitivity and specificity of PCT and CRP were comparable in our analyses; however, PCT levels had an inverse relationship with eGFR in patients with renal insufficiency but no infection." (PMID 25407928, 2014). "In addition, the level of ALB, CRP and ESR were significantly different between patients with and without renal insufficiency." (PMID 31620002, 2019).
unstable angina (172 papers, 2004 to 2026). "Women with angina and men with elevated levels of Hs-CRP, Hs-Troponin T and NT-proBNP were at higher risk of death during the pandemic period, consistent with other research." (PMID 39774287, 2025). "One study of 2554 patients with angina found a positive association between CRP and both the number and severity of atherosclerotic lesions at coronary angiography in a unadjusted analysis, although correlation coefficients were low13." (PMID 37500663, 2023). "Our previous study also demonstrated that higher CRP levels have a strong association with stable and unstable angina patients that required further molecular studies to discover their undeveloped signaling pathways." (PMID 35814945, 2022). "Other earlier studies observed the correlation of MHR with hs-CRP and found it was associated with slow coronary flow events of stable angina pectoris with normal coronary arteries by angiography." (PMID 34330221, 2021). "European Concerted Action on Thrombosis and Disabilities Angina Pectoris Study Group Production of C-reactive protein and risk of coronary events in stable and unstable angina." (PMID 33331459, 2021). "Baseline levels of CRP are elevated in patients with unstable angina and are associated with an unfavorable short-term prognosis." (PMID 30344267, 2018). "Baseline CRP levels in healthy individuals or in patients with stable angina are independent risk factor for cardiovascular events." (PMID 26631004, 2015). "It has also been demonstrated earlier that increased CRP levels among stable angina patients would confer greater risk of development of MI." (PMID 25822970, 2015). "One of the polymorphisms with higher expression levels was then associated with higher levels of serum C-reactive protein and unstable angina, and it is this form that was associated with more severe vasoconstriction in patients with RCVS." (PMID 24707417, 2014). "In our study, the inflammatory response was measured by elevated C reactive protein levels, and this was associated with the recurrence of angina or restenosis at 6 months, similar to previous reports." (PMID 25253465, 2014). "The European Concerted Action on Thrombosis and Disabilities (ECAT) Angina Pectoris Study found that CRP and BMI were significantly associated among 2,121 patients with angina pectoris, but no detailed analyses were presented." (PMID 22505974, 2009). "Furthermore, unstable angina patients with high CRP levels at discharge are associated with a higher risk of recurrent cardiovascular events or MI within one year." (PMID 39597855, 2024). "In addition, it was determined that increased high sensitivity C-reactive protein (hs-CRP) levels in these patients were associated with more severe angina pectoris and more active disease." (PMID 36959528, 2023). "Production of C-reactive protein and risk of coronary events in stable and unstable angina." (PMID 33331459, 2021). "Thus, in patients with stable or unstable angina, serum concentrations of CRP >3 μg/mL are associated with an increased risk of coronary events and in vitro concentrations of 5 μg/mL had significant inflammatory effects." (PMID 20157364, 2008). "CRP has been shown to be an independent predictor of adverse outcomes at 90 days in patients with unstable angina, 30-day mortality in patients with acute heart failure and 90-day mortality in patients with acute ischemic stroke." (PMID 40579468, 2025). "During the follow-up period, 37 patients with stable angina experienced cardiovascular events, and they had higher levels of CRP, TC, TG, and LDL-C, and lower levels of HDL-C than those who did not." (PMID 39507388, 2024). "Some studies have reported that patients with stable angina have higher levels of inflammatory markers, such as C-reactive protein (CRP) or procalcitonin (PCT), than control group, while others only supported high-sensitivity CRP." (PMID 39507388, 2024).
unstable angina (continued). "The pooled results showed that TXLC appears to have some efficacy in improving cardiac function and relieving angina symptoms, but there is limited evidence that it improves cardiovascular event rates, hemorheology, lipids, or hs-CRP." (PMID 38414926, 2024). "The patients with stable angina had significantly higher levels of CRP, TC, TG, and LDL-C, and lower levels of HDL-C than the control group." (PMID 39507388, 2024). "We found that patients with stable angina had higher levels of CRP, TC, TG, and LDL-C, and lower levels of HDL-C than control group." (PMID 39507388, 2024). "We found that CRP, TC, TG, and LDL-C were positively correlated with the CCS grade, indicating that higher levels of these parameters were associated with more severe angina symptoms and limitations." (PMID 39507388, 2024). "We found that patients with stable angina had significantly higher levels of CRP, TC, TG, and LDL-C, and lower levels of HDL-C than control group." (PMID 39507388, 2024). "Another meta-analysis found that elevated CRP levels were linked to Angina Pectoris (AP), particularly unstable AP, and were possibly a risk factor of major adverse events, and also, the authors noted that patients with AP syndromes may be prediagnosed by their serum CRP titers." (PMID 37873776, 2023). "The number of angina patients in the high hs-CRP group, i.e. five (15.63%) was significantly higher than the low hs-CRP group, i.e. two (2.78%) (P=>0.027)." (PMID 37273333, 2023). "The results revealed moderate-quality evidence for clinical efficacy, angina duration, CRP, EGG changes, TC, TG, LDL, PV, HS, and HCT." (PMID 37790809, 2023). "Similar outcomes were also seen in the current study, where 16.12% out of 32 patients with high levels of baseline hs-CRP came back with recurrent angina." (PMID 37273333, 2023). "We noticed that Shenxiong Putaotang has better effect in total effective rate and angina pectoris attacks, total effective rate and hs-CRP improvement and improvement of TC and TG." (PMID 36263128, 2022). "Measurements of CRP have been tentatively linked to cardiac health since the 1980s, with studies finding that CRP levels were raised in patients who had been diagnosed with AMI or angina." (PMID 35159397, 2022). "In support of this relationship, human Val/Met carriers with unstable angina have significantly elevated plasma CRP compared to Met/Met carriers with unstable angina." (PMID 34867148, 2021). "In our study, HCY < 17.55 μmol/L, together with preinfarct angina and CRP were proved to be independent predictors of SR in STEMI patients; among the 3 predictors, HCY < 17.55 μmol/L showed the most obvious statistical significance." (PMID 29940881, 2018). "Our 1997 epidemiological work on CRP in patients with angina, and studies by others in general populations, identified an association between increased baseline values of CRP and future incidence of cardiovascular disease." (PMID 30459761, 2018). "In patients with unstable angina, increased inflammatory activity was confirmed compared to stable angina patients by elevated high sensitivity C-reactive protein and serum amyloid A protein levels." (PMID 30210493, 2018). "The present study showed that in patients with STEMI, preinfarct angina, CRP level, and HCY < 17.55 μmol/L were independent predictors of SR." (PMID 29940881, 2018). "In patients with STEMI, HCY < 17.55 μmol/L, preinfarct angina and plasma CRP level were independent predictors of SR." (PMID 29940881, 2018). "This fact seems to be of paramount importance when considering different mechanisms responsible for CRP synthesis as well as dissimilar magnitudes of CRP release in MI versus unstable angina." (PMID 22446726, 2012). "Patients with unstable angina and CRP >3 mg/L at discharge are more likely to be readmitted for recurrent cardiovascular instability or MI within 1 year." (PMID 24049653, 2012).